CXCL12 (C-X-C motif chemokine ligand 12)
Diseases named in the same sentence as CXCL12 in open-access papers (continued):
Sharing a sentence is not in itself a finding about the gene and the disease.
tumor (continued). "To provide more evidence that IL-2 augments the TDLN B cell killer/effector function via the CXCR4/CXCL12 axis, we performed experiments to compare the CXCL12 production by 4T1 tumor cells in the presence or absence of IL-2." (PMID 27528023, 2016). "CXCL12 and its receptor CXCR4 were shown to be important for recruitment of immunosuppressive cells such as MDSC and Tregs in the tumor microenvironment and for tumor angiogenesis." (PMID 27590504, 2016). "In the context of a tumor, high concentrations of adenosine produced by CD73-expressing fibroblasts, tumor-infiltrating immune cells and/or tumor cells, may increase CXCL12 expression in fibroblasts themselves through A2BR." (PMID 27590504, 2016). "T cells are absent from regions of the tumor containing cancer cells, which are coated with the chemokine, CXCL12, and the FAP α+ CAFs are the principal source of CXCL12 in the tumor." (PMID 26985769, 2016). "In summary, nitration on Tyr7 under inflammatory conditions is a novel natural posttranslational regulatory mechanism of CXCL12 which may downregulate the CXCR4-mediated inflammatory and tumor-promoting activities of CXCL12." (PMID 27566567, 2016). "The tumour cells that produce bone metastasis express the chemokine receptor CXCR4, motif chemokine receptor 4 CXC in its membrane which responds to the chemoattractant signals generated by its ligand SDF-1, also known as CXCL12." (PMID 28105072, 2016). "The CXCL12/CXCR4 axis transactivates HER2 and promotes intraosseous tumor growth." (PMID 27809841, 2016). "Therefore, there is increasing evidence that CXCL12 and its specific receptor CXCR4 play an important role in many steps of tumor progression, such as invasion, migration, and proliferation of malignant cells." (PMID 27041792, 2016). "Our findings provide further evidence for the mechanism of CXCL12/CXCR4-mediated cellular proliferation, leading to novel therapeutic strategies to prevent tumor progression that may bring CXCL12/CXCR4-targeted therapy closer to clinical reality." (PMID 27439769, 2016). "To examine whether B cell-mediated 4T1 tumor cell death involves both Fas/FasL and CXCR4/CXCL12 pathways, we added anti-FasL and AMD3100 in the same experiment." (PMID 27528023, 2016). "Moreover, the relationship between serum concentrations of CXCL12/CXCR4 and clinicopathological parameters of tumor as well as the EC patients' survival was presented." (PMID 27041792, 2016). "Furthermore, tumor-derived chemokines that promote leukocyte migration and their entry into the CNS such as CXCL-10 and CXCL-12 are down-regulated, and the levels of TGF-β2 increase." (PMID 26291724, 2015). "In contrast, the ELR− CXCL12/SDF-1 chemokine has shown to promote cell migration and proliferation acting synergistically with VEGF via CXCR4 and/or CXCR7 receptors expressed in endothelial cells within the tumor microenvironment." (PMID 26062132, 2015). "In addition to the crucial role in migration, studies indicate that CXCL12 is involved in the pathogenesis of ALL, including facilitating metastasis, mobilizing tumor cells, and attracting of cancer stem cells within the tumor microenvironment." (PMID 27429863, 2015). "The tumor cells express functional receptors for growth factors, cytokines, chemokines, and other molecules involved in the angiogenic and inflammatory processes including VEGF, IL-6, IL-8, CXCL12, and PTGS2 (COX-2)." (PMID 29061946, 2015). "Tumor-derived CXCL10 and CXCL12 may have played a role in the massive infiltration of leukocytes to low generation xenografts." (PMID 26291724, 2015). "Because CXCL12 is the target molecule of HIF-1α, the hypoxic condition resulting from bevacizumab treatment could lead the tumour cells to produce CXCL12, which would in turn prompt the CXCR4+ cells to migrate into the tumour." (PMID 26635184, 2015). "Furthermore, miR-222 inhibited the recruitment of macrophages by targeting CXCL12 and inhibiting CXCR4 to suppress 4T1 tumor growth." (PMID 26689540, 2015).
tumor (continued). "As the caspase family is crucial to tumor cell apoptosis, caspase-3 and -8, and PARP expression were detected by western blotting to investigate whether CXCL12 affected the regulation of caspase-dependent apoptosis." (PMID 25997540, 2015). "We speculate that tumor cells with high expression of CXCR4 have strong potential for local invasion, and CXCL12 expressed in lymph nodes has a chemotactic effect on their directional migration." (PMID 25866764, 2015). "The CXCL12 and CXCR4 axis is involved in tumor progression, angiogenesis, metastasis, and survival." (PMID 26176534, 2015). "As investigated in vivo, using an orthotopic model of tumor cell implantation of chemokine receptor-overexpressing NB cells (IGR-NB8), the CXCR4/CXCR7/CXCL12 axis was shown to regulate NB primary and secondary growth, although without any apparent influence on organ selective metastasis." (PMID 25955316, 2015). "Immunohistochemical studies showed that in GBM CXCR4 and CXCL12 expression does not co-localize with tumor proliferating cells (identified by MIB-1 expressing cells) but they are both mainly localized in hypoxic regions, characterized by necrosis." (PMID 24904289, 2014). "In fact, CAFs release a great number of pro-angiogenic factors including VEGF, CXCL12, FGF, IL-8/CXCL8 and PDGF-C in the ECM to recruit other stromal cell types such as endothelial cells and their precursors in order to stimulate tumor angiogenesis and vasculogenesis." (PMID 24978438, 2014). "It should be noted that targeting CXCL12 and its receptor CXCR4 in mouse glioblastoma prevented HIF-1-mediated recruitment of pro-angiogenic TAM and TEM, reduced vasculogenesis and abrogated tumor growth after irradiation." (PMID 24634660, 2014). "It has been shown that CXCR4 is expressed in many tumor cells and those CXCR4-expressing tumors may show an organ-specific migration to the CXCL12-producing tissues/organs." (PMID 24659999, 2014). "The homeostatic chemokine CXCL12 was expressed outside malignant nodules whereas its receptor CXCR4 was identified within tumour but not on CD8+ cells." (PMID 24961933, 2014). "In these tumor cells, SEMA3F also blocks their migration induced by CXCL12 and S1P." (PMID 25068647, 2014). "Increased CXCL12/CXCR4 signaling has been reported after withdrawal of chemotherapy and shown to promote bone marrow derived endothelial progenitor cell mobilization and subsequent tumor homing, leading to an angiogenic rebound and regrowth of tumors." (PMID 25084358, 2014). "Consequently, the growth of tumor cells in the bone and in lung metastases was much less effectively inhibited by CXCR4 antibodies than CXCL12-guided and CXCR4-mediated chemotaxis of metastasizing tumor cells in the circulation." (PMID 24390633, 2014). "Tumor-bearing mice were treated at 4-day intervals by tail-vein bolus injections of the monoclonal anti-CXCR4 antibody (mAb 12G5), known to block the binding of CXCL12 to CXCR4 and to inhibit CXCL12-evoked chemotaxis in vitro." (PMID 24390633, 2014). "CXCL12/CXCR4 signaling plays an important and unique role in the regulation of stem/progenitor cell trafficking, inflammation, embryo/organogenesis, tissue/organ regeneration, and tumor progression, angiogenesis, metastasis, and survival." (PMID 25216273, 2014). "Furthermore, CXCL12 stimulates VEGF secretion in CXCR4-expressing, CD133+ CSCs from surgical specimens of human GBM and cell lines, promoting tumor angiogenesis via PI3K/AKT signaling." (PMID 24904289, 2014). "CXCL12 exerts also pro-angiogenic activity, recruiting CXCR4-positive, circulating bone marrow-derived cells and promoting tumor vasculature recovery after irradiation, as a consequence of treatment-induced hypoxia and HIF-1α activation, which results in increased CXCL12 expression." (PMID 24904289, 2014). "CXCL12 was also detected in ependymal cells lining the ventricle walls of a xenograft but not in the hippocampus infiltrated by tumor cells." (PMID 23527265, 2013).
tumor (continued). "While exogenous application of CXCL12 does stimulate migration of MSCs in response to tumor conditioned medium, recombinant CXCL12 failed to increase migration of MSCs treated with Nutlin-3." (PMID 24064862, 2013). "CXCR7 is a recently deorphanized CXCL12-scavenging receptor with so far not well-defined functions in tumor biology." (PMID 24040160, 2013). "The CXCL12/CXCR4 axis is involved in tumor progression, angiogenesis, metastasis, and survival, and promising results in preclinical tumor models indicate that CXCR4 antagonists may have antitumor activity in patients with various malignancies." (PMID 23987636, 2013). "Furthermore, emodin treatment led to the downregulation of migration and invasion induced by the ligand CXCL12 metastasis to the lungs in an orthotopic HCC mice model and CXCR4 expression in tumor tissues." (PMID 23472074, 2013). "Studies have also demonstrated that the activation of CXCR4 by CXCL12 stimulates a specific and significant proliferative response in GSCs, but not in differentiated tumor cells." (PMID 23961808, 2013). "CXCL12 is also constitutively expressed in tissues such as liver, lung, lymph nodes, adrenal glands and bone marrow, which indicates the important role of CXCL12/CXCR4 in tumor metastasis toward distant locations." (PMID 23555768, 2013). "Interestingly, the chemokine, CXCL12 (SDF-1), and its receptor, CXCR4, played an essential role in development of tumors in this model, as blockade of these molecules abrogated tumor growth." (PMID 23936541, 2013). "Patients whose tumours expressed high levels of CXCL12 had significantly poorer survival (P=0.026) than patients whose tumours failed to produce this chemokine." (PMID 22415233, 2012). "Moreover, and consistent with previous gene expression results, we show expression of CXCL12 protein by most EWS tumors (65%) and, explicitly, within the tumor microenvironment of virtually all (>95%) EWS cases." (PMID 23249693, 2012). "CXC chemokine ligand 12 (CXCL12)/Stromal cell-derived factor (SDF-1) is a member of the CXC chemokine family, which plays an important role in chemotaxis, haematopoiesis, angiogenesis and tumor spread and metastasis." (PMID 23098564, 2012). "Noteworthy, stromal CXCL12 expression was detectable in nearly all cases (in 95% (41/43) of therapy-naïve cases and in all metastatic lesions), regardless of CXCR4/ CXCL12 expression by tumor cells." (PMID 23249693, 2012). "Among those chemokines and their receptors, the stromal cell-derived factor-1 (also CXCL12) and its CX chemokine receptor 4 (CXCR4), a protein frequently overexpressed on the surface of human tumor cells of epithelial origin, have received considerable attention." (PMID 22496601, 2012). "Addition of AMD3100 alone did not interfere with spontaneous cell proliferation, suggesting a predominant role for paracrine (stroma-derived CXCL12) rather than autocrine (tumor cell-derived CXCL12) signalling." (PMID 23249693, 2012). "There was a 51-month survival advantage for patients whose tumours lacked CXCL12 expression, when compared with patients whose tumours expressed high levels of this chemokine." (PMID 22415233, 2012). "Moreover, CXCL12 has been demonstrated to contribute to neovascularization and EWS tumor growth in a mouse xenograft model." (PMID 23249693, 2012). "Suppression of FH2 activity alone via treatment with the FH2 inhibitor SMIFH2, which targets both mDia1 and mDia2 FH2 activity, was sufficient to drive amoeboid transition and blebbing in the absence of CXCL12, consistent with findings in other tumor cells." (PMID 23024796, 2012). "To determine whether CXCL12 effects were mediated by CXCR4, we treated cultures with AMD3100 and measured tumor cell growth by bioluminescence imaging." (PMID 22427929, 2012). "CXCL12 was heterogeneously distributed in tumor cells, with some cells displaying no detectable staining and others, strong immunoreactivity." (PMID 21410972, 2011).
tumor (continued). "Indeed, we have shown that hypoxia triggers the production of CXCL12 and vascular endothelium growth factor (VEGF) by EOC, with these two molecules acting in synergy to enhance tumor angiogenesis in vivo." (PMID 21410972, 2011). "PDAC tumors have been shown to express high levels of CXCL12 and CCL2, which could promote PDC migration into the tumor." (PMID 22190968, 2011). "There is therefore a need to determine whether CXCL12 status in EOC depends on its bioavailability and on the CXCR4/CXCR7 ratio in tumor cells, which would support an effect of CXCL12." (PMID 21410972, 2011). "The absence of CXCR4 methylation was associated with the tumor stage, size, histological grade, lymph node status, ESR1 methylation and CXCL12 methylation, metastasis and patient death." (PMID 22220212, 2011). "Hierarchical clustering analysis, including age at diagnosis, tumor grade, FIGO stage, Ki-67 index, CX3CL1, SDF-1/CXCL12 and GILZ immunostaining scores, distinguished two major clusters corresponding to low and high levels of proliferation and differing in terms of GILZ and CX3CL1 expression." (PMID 21750716, 2011). "Loss of DNA methylation in the promoter region of CXCR4 correlated with a more aggressive disease in terms of tumor stage, tumor size, SBR grade, 5demonstrated that concurrent epigenetic changes of CXCR4 and its ligand, CXCL12, correlated with shorter disease-free and overall survivals." (PMID 22220212, 2011). "Importantly, beside survival, chemokines in general, and CXCL12 in particular, are also powerful activators of the MAP kinase (ERK1/2) cascade, the most studied proliferative mechanism responsible of tumor growth." (PMID 20049170, 2010). "Mirroring our previous findings, net tumor burden was slightly decreased, but not statistically different, over time in CXCL12-Luc mice compared to GFP-Luc controls and was unaffected by Bim depletion." (PMID 20877573, 2010). "CXCL12 promoter hypermethylation in the first region (island 2) and second region (island 4) was correlated with lack of expression of the gene in tumour cell lines." (PMID 20109227, 2010). "In our initial experiments, we found that CXCL12(P2G) significantly inhibited spontaneous metastasis of 4T1.2 tumors to the lungs of tumor-bearing mice, without affecting primary tumor growth." (PMID 20849618, 2010). "Although our study shows the importance of CXCR7 in HCC invasion, angiogenesis and tumor growth, the role of CXCL12/CXCR7 interaction in tumor progression are not fully established." (PMID 20380740, 2010). "In contrast, no detectable levels of CXCL12 expression were observed in the highly aggressive tumour cell lines MDA-MB-435, MDA-MB-436 or MDA-MB-231." (PMID 20109227, 2010). "In the current study, we found that CXCL12/CXCR7 interaction promoted secretion of VEGF, a potent survival factor for endothelial cells, and one of the most prominent angiogenic factors produced by various tumor cells." (PMID 20380740, 2010). "Subsequent cell depletion experiments in immune competent mice revealed that CD8+, but not CD4+ cells were required for the anti-tumor effect, suggesting that cytotoxic T cells play an important role in CXCL12-mediated tumor inhibition." (PMID 20849618, 2010). "In addition to the phosphoproteomics results, we provide evidence from western blot validation that the tumor suppressor, programmed cell death factor 4 (PDCD4), is a previously unidentified phosphorylation target of CXCL12 signaling in all CLL cells probed." (PMID 20661426, 2010). "Although the role of CXCL12 in the promotion of invasive growth is well documented and the intracellular signals triggered by CXCR4 activation have been extensively investigated, the role of CXCL12/CXCR7 axis in regulating tumor growth of HCC is not yet known." (PMID 20380740, 2010).
tumor (continued). "Interactions between CXCR4 and its ligand CXCL12 (stromal cell-derived factor 1, SDF-1) play an important role in the directional regulation of hematopoiesis, migration of hematopoietic cells, angiogenesis, and migration of metastatic tumor cells." (PMID 20953377, 2010). "Because mononuclear phagocytes express both CXCL12 GPCRs and HB-EGF, we argued that the recruitment of mononuclear phagocytes to a site of metastasis such as liver through CXCL12 should induce a release of HB-EGF, which is expected to activate HER1 and favour tumour progression." (PMID 20946648, 2010). "We found that CXCL12(P2G) was able to inhibit both spontaneous and experimental metastasis, without affecting primary tumor growth." (PMID 20849618, 2010). "We found that blocking CXCR4 by expressing CXCL12(P2G) did not alter primary tumor growth, demonstrating the metastasis-specific effect of this antagonist." (PMID 20849618, 2010). "Indeed, SCLC cell lines and primary tumour cells express high levels of CXCR4, and CXCR4 ligand CXCL12 is constitutively expressed by bone marrow stromal cells." (PMID 19455144, 2009). "CXCL12 can bind another chemokine receptor, such as CXCR7, which is present on the surface of many different malignant cell types, on tumour-associated blood vessels, but not on normal vasculature." (PMID 19352387, 2009). "Recent studies have documented that CAFs are implicated in important aspects of epithelial solid-tumour biology, such as cancer progression, tumour growth, angiogenesis and metastasis by sustained expression of stromal-derived factor-1 (SDF-1), also known CXCL12." (PMID 19773759, 2009). "CXCR7 promoted the survival of tumour cells by preventing apoptosis, increased adhesion properties and dissemination, but did not mediate chemotaxis towards CXCL12." (PMID 19352387, 2009). "CXCL12-mediated tropism of malignant breast, lung, and other cancer cells for characteristic sites of metastatic disease has been attributed predominantly to signaling through receptor CXCR4 on tumor cells." (PMID 19484126, 2009). "In our study, tumor cells not only expressed CXCR4, but also CXCL12." (PMID 18983683, 2008). "Neutralization of CXCL12 in SCID mice abrogated metastasis of RCC to target organs expressing high levels of CXCL12; without altering tumor cell proliferation, apoptosis, or tumor-associated angiogenesis." (PMID 17083723, 2006). "Our findings demonstrate that tumor-associated angiogenesis, proliferation and apoptosis are not affected in the primary RCC tumors in animals treated with neutralizing anti-CXCL12 antibodies, as compared to control antibodies." (PMID 17083723, 2006). "Furthermore, endothelial cells, such as pulmonary endothelial cells have been shown to coexpress CXCL12 and vascular cellular adhesion molecule (VCAM)-1, thus mediating tumour-cell/endothelial-cell attachment." (PMID 16819541, 2006). "Additionally, B cells secrete various proangiogenic factors, including VEGF, stromal cell‐derived factor‐1 (CXCL12), and B‐lymphocyte chemoattractant (CXCL13), stimulating the formation of new blood vessels to provide essential nutrients and oxygen support for tumor growth." (PMID 41583906, 2026). "CXCR7 activation by CXCL12 was shown to bias its signalling to β-arrestin, which promoted EMT and metastasis through induction of YAP1 nuclear transportation, resulting in the downregulation of mi-RNAs and promoting expression of DCLK1, a tumour stem cell marker." (PMID 39982274, 2025). "Lastly, in a third developing approach in addressing CXCR4/CXCL12-mediated drug resistance in TNBC, pharmaceutical engineers are developing a nanoparticle-based delivery system to selectively direct the CXCR4 inhibitors and chemotherapeutics to the tumour tissue to limit systemic toxicity." (PMID 41002447, 2025).